PPARG (peroxisome proliferator activated receptor gamma)
Diseases named in the same sentence as PPARG in open-access papers (continued):
Sharing a sentence is not in itself a finding about the gene and the disease.
steatosis (continued). "Dysregulation of these FA signaling mechanisms could explain in part the protection against steatosis observed after liver (hepatocyte)-specific PPARγ knockdown (aLivPPARγkd)." (PMID 31121839, 2019). "Based on our analysis, it is predicted that the disruption in the regulation of transcription factors such as AP-1, PPARγ, and NF-κB could contribute to the liver progression from cirrhosis to steatosis and eventually to HCC." (PMID 30250040, 2018). "Moreover, supplementation of the HFD-rats with 5-caffeoylquinic acid, one of our cherry compounds, reduced macrophage infiltration and steatosis via PPARγ and NFκB signaling pathways." (PMID 30029691, 2018). "PPARG has also been reported to regulate hepatocyte lipogenesis and has demonstrated a prosteatotic role in the liver because mice with hepatocyte deletion of Pparg were protected from high-fat diet-induced steatosis." (PMID 29907129, 2018). "In hepatocytes, PPARγ may play a predominant role in the metabolic adaptation downstream of PI3K/Akt2 pathway, leading to steatosis HBx also increases the expression of PPARγ, an effect thought to result from C/EBPα activation." (PMID 29183361, 2017). "Lipid peroxidation and PPARγ-dependent steatosis are also mediated by troglitazone." (PMID 27659300, 2016). "Feminization was consistently associated with increased expression of peroxisome proliferator-activated receptor gamma (Pparg) but not other lipogenic transcription factors linked to steatosis." (PMID 26959237, 2016). "Finally, we also addressed the role of the nuclear transcription factor PPARγ in VPA-induced steatosis." (PMID 27034954, 2016). "Based on these results, we propose that VPA may enhance OLA-induced hepatocyte steatosis through the upregulation of PPARγ- and CD36-dependent lipid uptake, TAG synthesis, and lipid droplet formation." (PMID 27034954, 2016). "Many studies have demonstrated a link between elevated PPARγ expression and hepactic steatosis." (PMID 26083030, 2015). "However, in vitro or in vivo studies with PPARγ agonists have led to contradictory results regarding steatosis and IR development." (PMID 23024649, 2012). "Thus, a role for PPARγ as an inducer of steatosis in hepatocytes has been suggested, and our results also show upregulation of PPARγ mRNA and its target gene CD36 in liver by the HF–HS diet." (PMID 22762794, 2012). "Furthermore, Med1 deletion also affects PPARγ-regulated adipogenesis in mouse embryonic fibroblasts and the adipogenic steatosis induced by PPARγ overexpression in liver." (PMID 20885938, 2010). "Thus,although activation of PPARγ in liver contributes to thedevelopment of steatosis, inflammatory gene expression issuppressed." (PMID 17389767, 2007). "In liver, PPARγ is involved in triglyceride homeostasis and contributes to steatosis." (PMID 17389767, 2007). "In addition, the decrease in steatosis itself may also secondarily suppress CD36 expression by suppressing PPARγ, a transcriptional activator of CD36." (PMID 41178716, 2025). "Additionally, PPARγ agonism via pioglitazone improves both steatosis and fibrosis in MASH patients." (PMID 40065360, 2025). "Multiple studies demonstrated that PPARγ shifts far away from liver tissues by regulating downstream genes, reducing triglyceride accumulation in cells, and increasing cholesterol efflux, resulting in the inhibition of hepatic tissue steatosis and amelioration of hepatocellular injury." (PMID 39139977, 2024). "However, F53B is thought to have the capability of inducing steatosis through PPARγ." (PMID 38133364, 2023). "Notably, mice with PPARγ liver-specific deletion are resistant to steatosis." (PMID 36430444, 2022). "PPARγ upregulates proteins associated with lipid uptake, TAG storage, and the formation of lipid droplets, such as FABP4, fat-specific protein 27 (FSP27)/Cidec, CD36, monacylglycerol O-acyltransferase 1, and perilipin 2; then PPARγ hepatic expression promotes steatosis." (PMID 34361064, 2021).
steatosis (continued). "Thus, it has been suggested that the role of PPARγ in the activation of lipogenic genes may contribute to the development of steatosis." (PMID 34060475, 2021). "Besides hepatotoxin stress, this study also reveals that the absence of WDR13 per se renders the liver susceptible to steatosis owing to the upregulated PPARγ and p38α in the control (vehicle treated) Wdr13−/0 mice." (PMID 33292732, 2020). "Indeed, since increased PPARγ expression has been found in steatotic livers, it has been suggested that the role of PPARγ in the activation of lipogenic genes may contribute to the development of steatosis." (PMID 31930115, 2019). "Cd36 is another target gene of PPARγ that could promote steatosis." (PMID 27973423, 2016). "Troglitazone induced PPARγ levels selectively in the liver under pathophysiological conditions, and severe steatosis may result in the accumulation of the drug in lipid-rich hepatocytes, with subsequent lipid peroxidation, and predispose the liver to the development of fibrosis." (PMID 27659300, 2016). "The steatosis induced in these mice is likely due in part to induction of the fatty acid transporter Cd36 by peroxisome proliferator-activated receptor γ (PPARγ), as treatment with a PPARγ antagonist reduces the expression of liver Cd36 and decreases liver triglyceride content." (PMID 26959237, 2016). "Therefore, it is possible that upregulation of PPARγ by genistein in this study may contribute to the improvement of steatosis and necroinflammation in the liver sections of NASH + Gen rats." (PMID 26246839, 2015). "Moreover, peroxisome proliferative activated receptor-γ co-activator 1 (PPARγ) expression, a stimulator of endogenous SLC2A2 mRNA transcription and key regulator of the genes associated with steatosis liver, was enhanced by about 40% after the leucine treatment (P ≤0.05)." (PMID 25859286, 2014). "Indeed, it has been suggested that PPARγ’s role in the activation of lipogenic genes may contribute to the development of steatosis, as increased PPARγ expression has been found in steatotic livers." (PMID 24209497, 2013). "Moreover, PPARγ itself is required in a majority of metabolic tissues for regulation of insulin action and normal physiologic response to nutrients and it plays a critical role in the development of steatosis." (PMID 20981297, 2010). "Additional evidence demonstrates that IRF5, IRF6, and IRF8 are also play key roles in hepatocytes: IRF5 mediates Fas-induced apoptosis, IRF6 suppresses PPARγ to reduce lipid accumulation, and IRF8 aggravates steatosis through a BMAL1/PPARγ axis." (PMID 41614922, 2026). "We demonstrate that tilorone attenuated HFD-induced steatosis by restoring bone morphogenetic protein 9 (BMP9)-Smad1/5/8 signaling and upregulating peroxisome proliferator-activated receptor gamma (PPARγ) expression." (PMID 40423936, 2025). "To further investigate the role of MALAT1 in the protective effect of Ex-4 on steatosis, we quantified the expression of the SREBP-1 and PPARγ genes, known for their role in de novo lipogenesis." (PMID 40002783, 2025). "HIV patients with insulin-resistant lipodystrophia have altered hepatic expression of SREBP1 and peroxisome proliferator-activated receptor gamma (PPARγ), compared with NAFLD or control subjects, which contributes to pathogenesis of steatosis and fibrosis." (PMID 38137501, 2023). "The thiazolidinedione PPARγ agonist Pioglitazone (PIO) stimulates hepatic fatty acid oxidation and improves insulin sensitivity and reduces steatosis in NAFLD patients." (PMID 35203687, 2022). "Dual activation of PPARγ and PPARα has a favourable effect in ameliorating NASH by reducing inflammation, steatosis, and fibrosis." (PMID 35773269, 2022).
steatosis (continued). "Emerging evidence suggests that phosphorylated AMPK inhibits the downstream target proteins C/EBP, PPARγ, and SREBP-1c through inhibiting preadipocyte differentiation, reducing liver TG levels, and thus ameliorating steatosis." (PMID 35723408, 2022). "Given these modulations of liver triglycerides and steatosis, we next measured hepatic mRNA levels of key lipogenic mediators involved in ALD-steatosis, including FASN, SREBP1-c, ACC1 and PPARγ, by qPCR." (PMID 33815111, 2021). "Since PPARγ expression level is increased in NAFLD, obese, and T2DM patients, it was suggested that PPARγ acts as a pro-steatosis factor via the de novo lipogenesis and activation of lipogenic genes." (PMID 33923295, 2021). "The results will provide evidence for the role of TWIST and PPARγ in NAFLD, clarify their function in the adipogenesis process and provide new insights into steatosis-related diseases." (PMID 33879188, 2021). "Since, MCD diets increase the expression of hepatic PPARγ and CD36 in mice, it is plausible that these genes contribute to the development of steatosis and the subsequent progression to NASH in mice fed with MCD diets." (PMID 32411189, 2020). "Both PPARγ and CD36 contribute to the development of high-fat diet-induced steatosis in mice by upregulating steatogenic mechanisms that involve de novo lipogenesis (DNL) and fatty acid uptake." (PMID 32411189, 2020). "To date, the pharmacological activation of PPARγ with Thiazolidinediones (TZDs) and the use of novel TZDs with reduced ability to bind PPARγ have been studied as a potential therapy to reverse NASH and steatosis." (PMID 32411189, 2020). "The activity regulation of PPARα, PPARγ, and RXRα in mouse models of NASH was instead more representative of their activity in human livers with simple steatosis." (PMID 32660130, 2020). "In particular, the concurrent activation of hepatic Pparα and inhibition of Pparγ by supplemental nitrate suggest a potential application for the prevention and treatment of HFD-induced steatosis." (PMID 32001953, 2020). "PPARγ was another transcription factor, which was a part of our validated DEGs and showed a good correlation with NAS, steatosis and inflammation degree of the patients and the role of PPARγ in NAFLD is also well established." (PMID 31635436, 2019). "In summary, we demonstrated that elevated H19 expression is a characteristic molecular change in NAFLD, and H19 promotes hepatocyte steatosis, TG secretion and expression of NAFLD-related genes via activating PPARγ signal by sponging miR-130a." (PMID 31064820, 2019). "Treatment with BAR502 caused a ≈10% reduction of b.w., increased insulin sensitivity and circulating levels of HDL, while reduced steatosis, inflammatory and fibrosis scores and liver expression of SREPB1c, FAS, PPARγ, CD36 and CYP7A1 mRNA." (PMID 28202906, 2017). "Diet-induced steatosis reduced hepatic Pemt expression in control (Pparg-intact) mice, and the thiazolidinedione (TZD)-mediated activation of PPARγ in diet-induced obese control (Pparg-intact) mice reduced the expression of betaine homocysteine S-methyltransferase (Bhmt) and Cbs." (PMID 41929038, 2026). "PUFAs have also been shown to inhibit PPARγ expression and SCD1 activity, thereby limiting FA desaturation and lipid droplet formation, which may protect against steatosis." (PMID 40503664, 2025). "Therefore, the specific activation of PPARγ in hepatocytes versus non-parenchymal hepatic cells might explain discrepancies in efficacy between genetic predispositions and pharmacological impacts on steatosis in clinical settings." (PMID 40034783, 2025). "Many NR ligands have been linked specifically to steatosis, including LXR, PPARα, PPARγ, PXR, GR, FXR, CAR, ER, RAR, and AhR, yet AhR does not belong to the NR family." (PMID 38791241, 2024). "We then investigated whether PPARγ or NR2C2 mediated the effects of 9-HODE and 13-HODE on hepatocyte steatosis." (PMID 38071367, 2023).
steatosis (continued). "Furthermore, those observations were confirmed by qPCR examination of steatosis-related genes in which the expressions of CD36 and PPARγ were significantly changed accordingly with the DKK1 manipulations under HFD." (PMID 36410795, 2023). "Furthermore, the expression of γH2AX, HO1, PPARγ, and SREBP-1c increased significantly in liver tissues, suggesting that OA treatment leads to oxidative damage and steatosis in rat liver." (PMID 35185572, 2022). "To confirm whether PPARγ played an important role in OTA-induced steatosis, we treated HepG2 cells with GW9662, a potent antagonist of PPARγ." (PMID 34822586, 2021). "Among these, pioglitazone, a ligand for the nuclear transcription factor peroxisome proliferator-activated receptor gamma (PPAR-γ), and vitamin E, an anti-oxidant agent, have been shown to improve steatosis, inflammation, and ballooning, which are the histological features of NASH/NAFLD." (PMID 34208839, 2021). "Specifically, it has been proposed that the upregulation of PPARγ and CD36 in NAFLD might increase hepatic lipid uptake and promote the development of steatosis." (PMID 32411189, 2020). "Still, abundant steatosis is not an immediate outcome of the highly increased expression level of PPARG, FABP4, CD36, and LPL in the liver of the severly obese minipigs." (PMID 32205840, 2020). "It has been proposed that hepatic PPARγ and CD36 may increase the uptake of lipids by hepatocytes which could promote steatosis in mice fed a MCD diet." (PMID 32411189, 2020). "However as recalled above, induction of PPARγ by TZD, in particular pioglitazone, ameliorates steatosis and NASH." (PMID 28115925, 2016). "In the current study, we also found that mRNA expression of PPARγ was significantly lower in the FHD-SBS group than in the HFD group, demonstrating that a SBS-supplemented diet induced a reduction of PPARγ expression in the HFD-induced steatosis liver." (PMID 24905748, 2014). "PPARγ may also be involved in TRI-induced hepatosteatosis, as TCA also activates mouse PPARγ, and guinea pigs suffering from TRI-induced toxic liver injury showed fatty changes of the liver." (PMID 20709644, 2010). "Thus, simultaneous activation of Pparα and inhibition of Pparγ through nitrate supplementation may be a target for the prevention and treatment of HFD-induced steatosis." (PMID 32001953, 2020). "However, although modest therapeutic effects of TZD on steatosis of patients with NASH have been consistently reported, there is not a consensus in the effects that pharmacological activation of PPARγ may have on fibrosis in patients with NASH." (PMID 32411189, 2020). "Therefore, based on their known actions on lipid metabolism and homeostasis in the liver, PPARγ and CD36 may increase lipid uptake in hepatocytes and contribute to the progression of steatosis and steatohepatitis induced by MCD diets." (PMID 32411189, 2020). "Taken together, although PpargΔHep did not reduce the levels of plasma ALT nor steatosis, these data indicated that hepatocyte PPARγ and CD36 expressions could contribute to the upregulation of genes related to the progression of NASH." (PMID 32411189, 2020). "PPARγ Two randomized, double-blind, placebo-controlled trials (RDBPCT) have shown that pioglitazone [peroxisome proliferator-activated receptor gamma (PPARγ) agonist] significantly ameliorated steatosis and necroinflammation compared to placebo in diabetic NASH." (PMID 29247356, 2018). "Furthermore, our study suggested that hepatocyte PPARγ contribution to the progression of NASH may be independent of steatosis." (PMID 32411189, 2020). "As pharmacological modulation of PPARγ showed promising results on steatosis and necroinflammation in most, but not all, patients with NAFLD, whereas the effect on fibrosis is still undefined, we hypothesized that functional genetic variants may influence disease progression." (PMID 20825652, 2010).
steatosis (continued). "Hepatocyte PPARγ and/or CD36 expression did not contribute to the development of steatosis induced by the MCD diet." (PMID 32411189, 2020). "Hepatocyte-specific PPARγ and CD36 expression may not play a critical role in the development of steatosis induced by MCD diets, however, hepatocyte-specific PPARγ and CD36 may contribute to the progression of steatohepatitis in adult mice." (PMID 32411189, 2020). "Given our current finding of Smurf1 in protecting the liver from steatosis, a viable strategy to treat NAFLD may be to curtail the transcriptional activity of PPARγ by turning on Smurf1-mediated non-proteolytic ubiquitin modification." (PMID 30566427, 2018). "Interestingly, co-administration of A + S induced steatosis, displayed lower fibrosis levels than sucrose alone, diminished CAPN1 levels but displayed attenuated inhibition of calpain proteolytic activity and did not have increased PPARγ levels." (PMID 41468440, 2025). "However, there are conflicts about the role that hepatic PPARγ plays in the development of MCD-induced steatohepatitis since adenovirus-mediated overexpression of PPARγ with a cytomegalovirus promoter (not hepatocyte-specific) reduces fibrosis and steatosis in mice fed an MCD diet." (PMID 32411189, 2020).